CHRNA7 (cholinergic receptor nicotinic alpha 7 subunit)
Diseases named in the same sentence as CHRNA7 in open-access papers (continued):
Sharing a sentence is not in itself a finding about the gene and the disease.
lung squamous cell carcinoma (1 paper, 2021). "In fact, the higher expression of CHRNA7 in lung squamous cell carcinoma was associated with poor survival in the TCGA-LUSC cohort." (PMID 34771509, 2021).
lymph node metastasis (1 paper, 2021). "We found that high expression of CHRNA7 is highly correlated with lymph node metastasis (P = 0.010), tumor stage (P = 0.019), and smoking history (P = 0.048)." (PMID 33603170, 2021).
migraines (1 paper, 2021). "By examining the relationship between the clinical variables of migraine patients and the measurement of CHRNA7 gene expression levels, mean, median, and p-values were calculated." (PMID 34563047, 2021). "The number of reduced CNVs (<2) in the CHRNA7 gene was lower in patients with migraines than in the controls." (PMID 34563047, 2021). "The findings here are that, in terms of the relationship between the frequency of the migraine and CHRNA7 gene expression, it is observed that the gene expression is considerably reduced in individuals with a frequency of pain once or twice a week." (PMID 34563047, 2021). "In the migraine patients and controls, the expression data of the CHRNA7 gene compared to the ACTB control gene, and the relationship between copy number changes in the gene were examined; moreover, median and p values were calculated." (PMID 34563047, 2021). "In our migraine group, where peripheral blood samples were studied, the CHRNA7 gene was downregulated as in other diseases in the studies mentioned." (PMID 34563047, 2021). "Based on the ROC analyzes reported, CHRNA7 gene expression is thought to have potential as a putative regulator or a biomarker of migraine sensitivity." (PMID 34563047, 2021). "In this study, the expression of the CNVs in the CHRNA7 gene at the 15q13.3 location in migraine patients and revealing the gene expression and clinical linkage, and the potential of CNVs and/or gene expression as a biomarker and a new target in the treatment of the disease was investigated." (PMID 34563047, 2021). "The results indicate that there may be a link between the gain and loss of the CHRNA7 gene in the CNV region and the expression of the gene in migraine patients." (PMID 34563047, 2021). "In conclusion, decreased expression of CHRNA7 gene may contribute to migraine by inactivation of α7nAChR." (PMID 34563047, 2021). "The p-values were calculated by examining the relationship between clinical variables of migraine patients and CNV of the CHRNA7 gene." (PMID 34563047, 2021). "We investigated the effects of the CNV and gene expression at the location 15q13.3 in the Cholinergic Receptor Nicotinic Alpha 7 Subunit (CHRNA7) gene, which we believe to be effective in the migraine clinic." (PMID 34563047, 2021). "Methods: we evaluated changes in CHRNA7 gene expression levels and CNV of 15q13.3 in patients with migraine (n = 102, with aura, n = 43; without aura, n = 59) according to healthy controls (n = 120) by q-PCR." (PMID 34563047, 2021).
morbid obesity (1 paper, 2021). An excess of body weight, normally defined as an individual with a body mass index greater than 35 or a body weight greater than one hundred percent of ideal body weight. "We describe the case of a four-year-old female with CHRNA7 15q13.3 microdeletion presenting with morbid obesity due to impulsive food-seeking behavior." (PMID 33884253, 2021).
myopia (1 paper, 2024). "By contrast, compared with the NC group, the levels of LPCAT1 (P<0.05) and CHRNA7 (P<0.05) protein decreased after myopia induction for 4 weeks." (PMID 39625993, 2024). "Significantly, this study unveiled novel insights into the changes in retinal CHRNA7 and LPCAT1 expression associated with myopia, which ZJP administration effectively reversed." (PMID 39625993, 2024). "Nicotinic receptor agonists have been shown to prevent myopia development, suggesting that CHRNA7 activation may impede myopia progression." (PMID 39625993, 2024). "Similarly, following 4 weeks of myopia induction, CHRNA7 gene expression fell significantly (P<0.001)." (PMID 39625993, 2024). "While dopamine levels decrease in the LIM model, CHRNA7 activation could potentially inhibit myopia by enhancing retinal dopamine content." (PMID 39625993, 2024). "Therefore, we regard NOS2, LPCAT1, and CHRNA7 as the core targets of ZJP for anti-myopia." (PMID 39625993, 2024). "This investigation provides the first evidence of ZJP’s multifaceted effectiveness in managing myopia, highlighting its impact on multiple components, targets, and pathways, including the novel involvement of LPCAT1 and CHRNA7 in myopia pathogenesis." (PMID 39625993, 2024). "Nonetheless, nicotine did not influence the reduction in dopamine and 3,4-dihydroxyphenylacetic acid (DOPAC) levels in form deprivation myopia (FDM), suggesting that changes in dopamine content in FDM might not explain why decreased CHRNA7 expression fosters myopia development." (PMID 39625993, 2024).
non-alcoholic fatty liver disease (1 paper, 2025). "CHRNA7 has been implicated in the regulation of inflammation in non-alcoholic fatty liver disease, while CXCR5 is known to play a role in cancer-related inflammation and immune responses." (PMID 40705171, 2025).
omphalocele (1 paper, 2012). Omphalocele is an embryopathy classified in the group of abdominal celosomias and is characterized by a large hernia of the abdominal wall, centered on the umbilical cord, in which the protruding viscera are protected by a sac. "Ablation of the Chrna7:Cre cell lineage in embryos from crosses with conditionally expressed attenuated diphtheria toxin results in precise developmental defects including omphalocele (89%) and open spina bifida (SB; 80%)." (PMID 22473653, 2012).
periodontitis (1 paper, 2025). An acute or chronic inflammatory process that affects the tissues that surround and support the teeth. "The increased expression of Vnsl1 and Chrna7 could reflect early attempts at neuronal repair and plasticity in response to systemic infections including periodontitis." (PMID 40171450, 2025).
Photophobia (1 paper, 2021). Excessive sensitivity to light with the sensation of discomfort or pain in the eyes due to exposure to bright light. "The loss and gain of CNV count for the CHRNA7 gene, which is observed to have an important place in this pathway, is thought to contribute to the symptoms of photophobia in patients related to the loss of function of these receptors." (PMID 34563047, 2021).
Prader-Willi syndrome (1 paper, 2017). "MEIS2 maps to 15q14 distal to the Angelman/Prader-Willi syndromes genomic region on 15q11.2q12 and the CHRNA7 gene on 15q13.3 (located 5 Mb from MEIS2)." (PMID 28934986, 2017).
pulmonary sarcoidosis (1 paper, 2019). Sarcoidosis affecting the lung parenchyma. "CHRNA7 is associated with pulmonary sarcoidosis, whose expression is significantly elevated in peripheral blood mononuclear cell in patients with pulmonary sarcoidosis compared with healthy controls." (PMID 30700303, 2019).
Rett syndrome (1 paper, 2013). A severe neurodevelopmental disorder affecting the central nervous system. "Patients with Rett syndrome or even those with typical ASD, revealed significantly reduced CHRNA7 expression in the frontal cortex compared with controls, suggesting that transcription of CHRNA7 is modulated by these regulatory elements and is involved in ASD-like phenotypes." (PMID 24204377, 2013).
sarcoidosis (1 paper, 2019). Sarcoidosis is a multisystemic disorder of unknown cause characterized by the formation of immune granulomas in involved organs. "Therapeutic activation of the CHRNA7-dependent nicotinic anti-inflammatory pathway represents a theoretical intervention to prevent progression of sarcoidosis." (PMID 30700303, 2019).
spina bifida (1 paper, 2012). A congenital neural tube defect in which vertebrae are not fully formed. "We report these newly designed mice and the unanticipated finding that genetic ablation of the α7 cell lineage in embryos of the Chrna7:Cre × ROSA26-loxP(DTA) produced several defects, one of which is lumbosacral spina bifida (SB)." (PMID 22473653, 2012).
tongue cancer (1 paper, 2025). A malignant neoplasm affecting the tongue. "The qRT‐PCR analysis revealed that CHRNA5 expression was highest, followed by CHRNA7 and then CHRNA3, in SCC‐4 tongue cancer cells." (PMID 41201200, 2025). "We integrated analyses of SCC‐4 tongue cancer cells with CHRNA overexpression, immunohistochemistry of OSCC pathological specimens, and data from the cancer genome atlas (TCGA), DepMap, and Puram 2017 to assess CHRNA3, CHRNA5, and CHRNA7 in OSCC/HNC." (PMID 41201200, 2025).
type 2 diabetes (1 paper, 2023). "Thus, the aim of this work is to identify the effects of different types of exercises on the expression of the CHRNA7, CHRFAM7A and tumor necrosis factor-α (TNF-α) in leukocytes of healthy normal weight (HNW), and overweight with type 2 diabetes (OT2D) individuals." (PMID 36831101, 2023).
ulcerative colitis (1 paper, 2016). An inflammatory bowel disease involving the mucosal surface of the large intestine and rectum. "Colon biopsies of ulcerative colitis (N = 33) confirmed increased expression of CHRFAM7A and decreased in CHRNA7 expression (p < 0.001)." (PMID 27051591, 2016).
viral infection (1 paper, 2021). "Chrna7 also expresses in rainbow trout macrophages and plays a role during viral infection in the zebrafish." (PMID 34445566, 2021). "Additionally, we tested the ability of agonists and antagonists of Chrna7 to alter the neural circuit and shed light on its functional properties during viral infection." (PMID 34445566, 2021).
cancer (12 papers, 2017 to 2025). A tumor composed of atypical neoplastic, often pleomorphic cells that invade other tissues. "We identified an unexpected role for CHRNA7 in cancer in the regulation of tumor-associated immune cells and activation of adaptive immune responses." (PMID 40653990, 2025). "The nicotinic cholinergic receptor α7 (α7 nAChR/NACHR7, encoded by CHRNA7 gene, and called CHRNA7 through the manuscript), a ligand-dependent Ca2+-channel, has been particularly linked to the progression of smoking-related cancers." (PMID 29545933, 2018). "Since our GSEA analysis found that CHRNA7 expression is associated with JAK2-STAT3 signaling in different cancers, we test the hypothesis that nicotine enhances tumor-initiating capacity by activating CHRNA7 and subsequently the JAK2/STAT3 pathway." (PMID 33603170, 2021). "To demonstrate the role of CHRNA7 in metformin-inhibited CIC properties, we estimated the mRNA and protein levels of CHRNA7 in two ESCC cancer cell lines, when they were treated with metformin (0.8 mM) and nicotine alone or in combination." (PMID 33603170, 2021). "Here we report that nicotine enhances ESCC cancer malignancy and tumor-initiating capacity by interacting with cholinergic receptor nicotinic alpha 7 subunit (CHRNA7) and subsequently activating the JAK2/STAT3 signaling pathway." (PMID 33603170, 2021). "This positions CHRNA7 as a promising therapeutic target in cancer immunotherapy." (PMID 40653990, 2025). "Furthermore, the release of acetylcholine from T cells, which stimulates CHRNA7-expressing macrophages, reinforces the relevance of CHRNA7 signaling and the importance of CHRNA7 action in inflammation and cancer." (PMID 40653990, 2025). "Interestingly, the specific Chrna7 antagonist MG624 was lately shown to also act on Chrna9 containing hetero-pentamers in cancer cells." (PMID 33815383, 2021). "We used ESCC, nicotine-related cancer, as a model system to demonstrate that the combinatory therapy synergistically inhibits nicotine-enhanced CIC properties by targeting CHRNA7." (PMID 33603170, 2021). "Multiple lines of evidence indicate that homopentameric nAChRs of CHRNA1, CHRNA3, CHRNA4, CHRNA5, CHRNA6, CHRNA7, and CHRNA9 are involved in cancer initiation and progression." (PMID 33603170, 2021). "Among them, CHRNA7 and CHRNA9 have been reported to be capable of inducing cancer stem cell-like cells (CSC) or cancer-initiating cells (CIC)." (PMID 33603170, 2021). "In these specific intergroup DE genes, BCL11A, VPREB3, CD79B, CHRNA7, and SWAP70 that all involved in B cell proliferation and activation, would likely impact B cell function in MDV pathogenesis and malignant tumor formation." (PMID 30922224, 2019). "For example, studies outside the field of cancer have established the functional relevance of CHRNA7 in tissue macrophages, but this has not been established in tumor-associated immune cells." (PMID 40653990, 2025). "Moreover, CHRNA7 was overexpressed in lungs with cancer compared to non-cancer-involved “normal” lungs by over 30%." (PMID 34771509, 2021).
tumor (11 papers, 2018 to 2025). "Supported by data demonstrating that tumor-associated CD11c+ immune cells highly expressed CHRNA7, we propose that CHRNA7 is a novel biochemical target for activating tumor-associated DCs that promote adaptive immune responses." (PMID 40653990, 2025). "We show that loss of CHRNA7 in KO mice increased tumor burden and reduced animal survival that was associated with decreased numbers of DCs." (PMID 40653990, 2025). "We observed that tumor-bearing CHRNA7KO mice had decreased survival and increased tumor burden linked to a CHRNA7-mediated reduction in immune cell activation." (PMID 40653990, 2025). "We observed that the highest levels of CHRNA7 expression were observed on CD11cHiCD11b+ tumor-associated cells (top right, red arrow), a myeloid cell subset associated in general with APCs." (PMID 40653990, 2025). "Together, these changes suggested that CHRNA7 mediated a reprogramming of gene expression in tumor-associated immune cells that was relevant in tumor progression." (PMID 40653990, 2025). "The integration of genetic and pharmacologic studies highlighted the role of CHRNA7 in tumor-associated immune modulation and supported the therapeutic potential of CHRNA7 agonists in TNBC." (PMID 40653990, 2025). "We provide evidence here that CHRNA7 functions as a novel therapeutic target in tumor-associated immune cells, with a particular focus on tumor-associated APCs." (PMID 40653990, 2025). "To localize CHRNA7-dependent changes in tumor-associated immune cells, we immunostained E0771 tumors from CHRNA7KO versus WT mice with an anti-CD11c antibody." (PMID 40653990, 2025). "The reduction in tumor burden and increased survival that we observed using the CHRNA7 agonist AR-R17779 in combination with an immune checkpoint inhibitor suggested that tumor-associated CHRNA7+ immune cells are novel therapeutic targets." (PMID 40653990, 2025). "Based on the efficacy of AR-R17779 treatment on reducing tumor progression in several models of TNBC, and evidence that CHRNA7 action in tumor-associated immune cells is relevant in adaptive immunity, we tested the effect of combination therapy of AR-R17779 with an anti-PD-L1 antibody." (PMID 40653990, 2025). "The CHRNA7 gene belongs to a family of ion channels that mediates fast signal transmission at the synapse, is associated with multiple neurological and psychiatric disorders, and plays a role in tumor progression in multiple cancers." (PMID 39387520, 2024). "Our findings suggest that AR-R17779 as a monotherapy was effective as a stimulator of CHRNA7 signaling, which activated myeloid immune cells leading to increased T cell–mediated tumor clearance to reduced tumor burden and increased survival." (PMID 40653990, 2025). "Taken together, these findings support a model in which CHRNA7 signaling promotes the activation of myeloid immune cells that, in turn, stimulate T cell mediated tumor clearance, reducing tumor burden and improving survival." (PMID 40653990, 2025). "Given the well-established role of SOX2 in tumor-initiating cells, we experimentally demonstrated the parallel relationship between CHRNA7 and SOX2 when CHRNA7 is either knocked down or overexpressed." (PMID 33603170, 2021). "The overexpressed CHRNA7 was capable of not only enhancing tumor formation but also generating bigger tumors." (PMID 33603170, 2021). "Simultaneous qRT-PCR and FACS analyses confirmed expression of CHRNA7 in tumor cells but also revealed certain discrepancies." (PMID 29545933, 2018). "Similarly, staining CD45+ peripheral blood leukocytes with fluorescent α-Bgtx identified CHRNA7+ leukocytes in the circulation of tumor-bearing mice." (PMID 40653990, 2025). "Although there are many studies on nicotine, tobacco-related carcinogens, and nicotinic receptors in tumor cells outside the focus of our study, no studies to date have identified a role for CHRNA7 in tumor-associated host immune cells." (PMID 40653990, 2025).